IL7 (interleukin 7)
Diseases named in the same sentence as IL7 in open-access papers (continued):
Sharing a sentence is not in itself a finding about the gene and the disease.
tumor (continued). "We found that M6PRlow IL-7 effectors are shielded against Treg suppression and thereby able to regress the tumor size on adoptive T-cell transfer substantially." (PMID 28496990, 2017). "Here we provide direct evidence that administration of recombinant IL-7 can potentiate the expansion, maintenance and function of adoptively transferred tumor-reactive CD4+ T cells." (PMID 28939858, 2017). "In summary, our study is the first to demonstrate IL-7 elevation in CRC in association with lymph node involvement and tumor location." (PMID 27866242, 2017). "CD4+ effector T cells that were primed in TDLNs and stimulated with IL-7 and IL-23 inhibited tumor progression more strongly than those stimulated with IL-2 and IL-7 when they were transferred into lymphopenic tumor-bearing mice." (PMID 28854279, 2017). "After treatment period, cytokines, Interleukin 2, IL-6, IL-7, IL-10, IL-15, 1 L-17 and TNFα in CT-26 tumor bearing BALB/c mice serum were analysed." (PMID 29246138, 2017). "Occupying central position in innate and adaptive immunity, IL-7 with its repertoire of antibacterial, anti-fungal, anti-viral, and anti-tumor activities is considered as “a critical enhancer of protective immunity”." (PMID 27866242, 2017). "The results indicate that CTX preconditioning is a prerequisite for donor CD4+ T cells to acquire IL-7 responsiveness, which correlates with the functional status of tumor-reactive CD4+ T cells." (PMID 28939858, 2017). "An interesting observation reported in this study is a significant variation in systemic IL-7 levels with respect to tumor location." (PMID 27866242, 2017). "Of note, similar to our previous research with IL-2 and IL-7/15-expanded cells co-cultured with irradiated 4T1 tumor cells, we found that IL-7/15-cultured cells produced less IFN-γ than did the IL-2-cultured T cells." (PMID 28146052, 2017). "Similar to the antigen-free conditions, IL-2-generated CART cells which were exposed to antigen-expressing tumor cells and IL-2, IL-7, or IL-15 showed enhanced expansion over other cytokines, with IL-15-exposed cells showing the least apoptosis." (PMID 27409425, 2016). "In the current study we provide evidence that CD8+ T cell-mediated tumor rejection in response to recombinant IL-7 (rIL-7) therapy is strictly dependent on IL-7R+ host cells." (PMID 27447484, 2016). "In the present study, we have shown that vaccination with tumor cells co-expressing IL-21 and IL-7 elicited potent antitumor responses in both prophylactic and therapeutic tumor models." (PMID 27571893, 2016). "Pre-treatment of T cells with IL-7 and IL-15 or IL-15 and IL-21 was shown to increase T memory cell functions and anti-tumor activity of CAR-T cells." (PMID 26999211, 2016). "More importantly, we identify an intricate interplay of IFN-γ and IL-7 signalling in TILs that dictates anti-tumour immune responses and therapeutic effects of combination therapy." (PMID 27498556, 2016). "In contrast to the 100% protection in WT mice, combination therapy failed to cure Il7r−/− tumour-bearing mice, which rapidly died within 20 days post-tumour inoculation, reflecting a critical role of IL-7-IL-7Rα signalling in combination therapy." (PMID 27498556, 2016). "It remains to be tested if this interdependent loop between IFN-γ and IL-7 signalling pathways can be extended to human tumours." (PMID 27498556, 2016). "The injection of recombinant IL-7 (rIL-7) circumvents this problem and boosts anti-tumor T cell responses." (PMID 27447484, 2016). "85% of mice in the 16-21/7 group stayed tumor-free, while only 40% and 20% of mice in the 16–21 group and the 16-7 group were immune to lethal tumor challenge, which suggested a synergy between IL-21 and IL-7 when co-expressed in whole-cell vaccines." (PMID 27571893, 2016).
tumor (continued). "Preclinical ACT models, in which the effect of exogenous IL-7 and IL-15 on tumor outgrowth has been tested, demonstrated that both cytokines can improve tumor control, including in vaccinated lymphodepleted or immunodeficient hosts." (PMID 27656185, 2016). "In this study, adjuvant activity of the IL-21 and IL-7 combination was tested in transplanted murine tumor models using lentivirally transduced whole-cell vaccines." (PMID 27571893, 2016). "As elucidated previously, CD4+ and CD8+ T cells take center stage in bolstering the antitumor immunity elicited by IL-21 and IL-7 co-expressing tumor cell vaccine." (PMID 27571893, 2016). "These preliminary data suggested that vaccination with IL-21 and IL-7 co-expressing tumor cells exhibited good safety profile, with negligible, if any, side effect." (PMID 27571893, 2016). "The moderate performance of IL-7 under antigen stimulation conditions ex vivo was consistent with its modest effect after injection to tumor-bearing hosts, although it induced higher frequencies of Tscm in antigen-free conditions." (PMID 27409425, 2016). "To circumvent chronic immune defects in Il7r−/− mice, we blocked IL-7 signalling in MB49 tumour-bearing mice before combination therapy." (PMID 27498556, 2016). "Among the various cytokines, the combination of CART cells and IL-15 or IL-21 administration mediated the best anti-tumor response, followed by IL-2 and IL-7, whereas IL-18 and only CART cells treated mice had the heaviest tumor burden." (PMID 27409425, 2016). "These facts suggested that CD4+ and CD8+ effector T cells were important participants in the antitumor immunity triggered by IL-21 and IL-7 co-expressing tumor cell vaccine, while NK cells are dispensable in such a process." (PMID 27571893, 2016). "IL7R, a receptor of interleukin 7, can influence the malignancy proliferation by the tumor microenvironment." (PMID 27821810, 2016). "Cytokines like IL-7, when secreted, stimulate immune effector cells and enhance tumor cell recognition by cytotoxic effector cells." (PMID 27401917, 2016). "IL-7 administration is tolerated better in humans, but anti-tumor efficacy requires further evaluation." (PMID 27656185, 2016). "In sum, both suppression of tumour growth and improved mouse survival by combination therapy require intact IL-7 and IFN-γ signalling in T cells." (PMID 27498556, 2016). "As an adjuvant, IL-7 enhances long-term tumor antigen-specific CTLs responses in both quantity and quality after immunization with recombinant lentivector." (PMID 25955647, 2015). "Although using IL-2 to stimulate the proliferation of anti-tumor T cells in culture remains the standard clinical approach, we were encouraged by our results with IL-7/15 to add or substitute IL-21 to our expansion regimen." (PMID 25903148, 2015). "A set of preclinical trials has proven that IL-7 can prolong the survival of tumor-bearing hosts in several tumor models." (PMID 25955647, 2015). "The main function of IL-7 is the control of B and T lymphopoiesis, but it is also important for the tumor process and the correct bone homeostasis." (PMID 26064994, 2015). "There has not been good data to demonstrate that IL-7 receptor expressed on solid tumors is functional or that IL-7 contributes to tumor growth." (PMID 25955647, 2015). "The co-administration of PAP-GMCSF, -IL2, -IL4 and -IL7 significantly prevented the tumor induction of PAP-RM9 cancer cells." (PMID 25632844, 2015). "The co-administration of PAP-GMCSF, -IL2, -IL4 and -IL7 significantly prevented tumor induction and inhibited tumor growth in the PAP-expressing tumors, yet not in the PSA-expressing tumors." (PMID 25632844, 2015). "The second mechanism is based on the secretion of IL-7 observed in the normal stromal fibroblasts of the Ad-REIC-injected tumor sites." (PMID 24527065, 2014).
tumor (continued). "The markedly anti-tumor activity of administration of IL-7/HGFb in vivo correlated with a significant increase in the number of tumor-infiltrating CD4+ and CD8+T cells." (PMID 24465710, 2014). "When the REIC/Dkk-3 gene is overexpressed by Ad-REIC in the fibroblasts of the treated tumor, significant levels of IL-7 are expressed and secreted in the cells." (PMID 24527065, 2014). "We found an increase of the level of IL-7 in four patients presenting moderate stages of tumor concomitant with a decrease of the level of GM-CSF." (PMID 24551818, 2014). "IL-7 synergizes with IL-12 or IL-21 to enhance anti-tumor immunity through the augmentation of cytotoxic T cells function." (PMID 24465710, 2014). "When Ad-REIC-infected NHF were mixed with untreated cancer cells and the mixture was transplanted into mice, the growth of the cancer cells was significantly suppressed, suggesting an indirect tumor-suppressive effect of Ad-REIC mediated by IL-7." (PMID 24498395, 2014). "The Ad-REIC-induced synergistic secretion of REIC/Dkk-3 proteins and IL-7 cytokines at the treated tumor site is important for autologous cancer vaccination by the agent." (PMID 24527065, 2014). "Our data showed that when given in the same dose, OXP plus IL-7 is significantly more effective than IL-7 or OXP alone in inhibiting tumor growth." (PMID 24465710, 2014). "Our data show OXP plus IL-7 is significantly more effective than IL-7 or OXP alone in inhibiting tumor growth in vivo." (PMID 24465710, 2014). "Interleukin-7 (IL-7) can potentially enhance immune responses against tumor, while oxaliplatin (OXP), a platinum-based drug, can promote a favorable immune microenvironment and stimulate anticancer immune responses." (PMID 24465710, 2014). "For example, it has been demonstrated that tumor cell lines transfected with the IL-7 gene reduced T-cell–dependent tumorigenicity in murine models." (PMID 24465710, 2014). "Toll-like receptor ligands and homeostatic cytokines, like IL-7 and IL-15, have been employed to promote the generation and expansion of tumor-specific T cells." (PMID 23935927, 2013). "Correlation analysis revealed significant positive correlations between tumor TL and peripheral levels of three cytokines (IL-7, IL-8 and IL-10)." (PMID 23383336, 2013). "Adding to the complexity though, is the fact that tumor TA was inversely correlated to IL-7 and IL-8, as well as to T/N RTL ratio, in the present study." (PMID 23383336, 2013). "This serum IL-7 increase seems to directly depend on tumor production: a strong IL-7 expression was detected in tumor masses originated in a human-in-mice model of bone metastases and in human bone metastatic biopsies." (PMID 23710201, 2013). "Observations of this set of immunological effects lead to the further testing of IL-7 in various preclinical tumor models." (PMID 22383042, 2012). "IL7 is essential for survival and memory formation of tumor-reactive T cells, and neutralization of IL7 after CTX administration diminishes the number of tumor-reactive T cells in an adoptive transfer model." (PMID 22400040, 2012). "IL-7 protected human T cells after a short co-culture with tumor cells in vitro, and inhibitors of PI3K/AKT pathway and siRNAs against Mcl-1 and Bim were used to evaluate the role of these signaling pathways in IL-7 protection." (PMID 22680924, 2012). "IL-7 has been shown to enhance the T cell response against chronic viral infections and tumours and we have previously reported its role in the T cell response to systemic challenge by Listeria monocytogenes." (PMID 23189186, 2012). "An increased expression of mouse-derived cytokines IFNG and interleukin 7 was found in VEGFA165 tumours, both described to induce SMAD7 expression." (PMID 22045186, 2011). "The opposite flank injection group was useful for serum IL-7 level comparisons, in order to discriminate production related to bone invasion from production by tumor mass alone." (PMID 20067635, 2010).
tumor (continued). "Both tumor cells and bone stroma can produce IL7 but cross-talk between the two increases production, as shown both in humans and in the described mice model." (PMID 20067635, 2010). "In detail, bone invaded by tumor cells showed a stronger level of IL-7 expression than contralateral bone, where IL-7 was expressed only by stromal cells." (PMID 20067635, 2010). "Staining for IL-7 of the bone implanted contralateral to the tumor showed stromal cells positive for IL-7 expression, as expected and according to the literature." (PMID 20067635, 2010). "BLNK is a tumor suppressor that regulates IL-7-dependent survival of pre-B cells via direct inhibition of JAK3, indicating a crucial role of JAK3 in pre-B cell proliferation." (PMID 20149240, 2010). "IL-7 expression by A549 cells was evaluated, showing a high IL-7 expression by tumor cells of epithelial origin." (PMID 20067635, 2010). "The analysis of bone invaded by tumor cells and bone contralateral to the tumor mass, showed a different intensity of IL-7 expression." (PMID 20067635, 2010). "Our mice model of bone invasion by contiguous tumor mass showed similar histology and IL-7 patterns compared to human pathology." (PMID 20067635, 2010). "Splenic T cells from naïve mice were primed ex vivo with DC-Ad-MAGE-1 in the presence of IL-2 and IL-7 to elicit cytolytic reactivity against tumor cells." (PMID 20420712, 2010). "In fact, the highest IL-7 serum levels were detected in the experimental group where tumor cells invaded the human bone target." (PMID 20067635, 2010). "IL-7 stimulates cytotoxic T-lymphocyte responses and down-regulates tumour production of the immunosuppressive growth factor, TGF-β." (PMID 18279524, 2008). "In murine models, intra-tumoural administration of dendritic cells modified with an adenoviral vector containing IL-7 led to tumour regressions and immunologic memory far superior to that seen with direct intratumoural injection of the AdIL-7 vector." (PMID 18279524, 2008). "By Real-Time PCR, we quantified DKK-1 and IL-7 gene expression on micro-dissected tumour and healthy tissue sections." (PMID 18978943, 2008). "Since IL-7 involvement in bone metastasis was previously demonstrated in other tumours, we investigated this issue showing an increase in serum IL-7 levels in CaP patients with and without bone lesions." (PMID 18978943, 2008). "Literature data support the IL-7 production by different tumor types apart from stromal cells in bone microenvironment." (PMID 17205128, 2006). "Some human solid tumors produce high IL-7 levels, suggesting a potential IL-7 role on tumor development and progression." (PMID 17205128, 2006). "Moreover, CAR-T cells cultured with IL-7+15 or IL-2+7+15 maintained sustained cytotoxicity and exhibited increased antitumor cytokine production during repeated tumor challenges." (PMID 41892338, 2026). "Encouragingly, the in vivo immune stimulation activities of the Fc-IL-7/Neo-7s also translated into anti-tumor activities where the efficacy of tumor growth delay was correlated with the binding affinities to IL-7Rα determined in the yeast display and SPR assays." (PMID 41542752, 2026). "However, recent studies have shown that fibroblasts expressing IL-7 are localized at tumor margins and interact directly with cancer cells, promoting their stemness and aggressiveness." (PMID 41597220, 2026). "We analyzed gene expression patterns and performed repetitive tumor killing assays to assess the ability of CAR-T cells expanded with IL-2 + IL-7 + IL-15 compared with IL-2 alone to maintain proliferation and cytotoxic function across multiple rounds of tumor cell exposure." (PMID 41892338, 2026). "All Fc-fused IL-7 treatments showed significant tumor suppression compared to the Fc control (human IgG-1 Fc with LALAPG mutation), with Fc-fused Neo-7 (Q6PT45I) being the most potent, followed by Fc-fused Neo-7 (Q6P) and Fc-fused WT-IL-7." (PMID 41542752, 2026).
tumor (continued). "The second-generation IL-7 drug, NT-I7 (efineptakin alfa), uses a hybrid human IgG/IgD Fc domain for half-life extension (T1/2=60.8–139.7 hr), which significantly improves its anti-tumor activities." (PMID 41542752, 2026). "RJW-58 enhanced IL-7 secretion and exerted an anti-tumor effect." (PMID 40707961, 2025). "This suggests that T cell-based immunotherapies, such as ICIs, chimeric antigen receptor T cells (CAR-T), or bi-specific T cell engagers, may produce synergistic effects when combined with an autologous tumor cell vaccine loaded with IL-7-expressing NDV." (PMID 40957993, 2025). "Similarly, in patient-derived xenograft models of ovarian cancer receiving an intraperitoneal infusion of peripheral blood mononuclear cells, intratumoral TILT-517 resulted in significant tumor inhibition compared to a non-IL7-expressing oAd." (PMID 40957993, 2025). "Although no single inflammatory protein was linked to all tumor types, IL‐7 and IL‐8 consistently showed causal associations with both cNENs and rNENs with concordant effect directions." (PMID 41458898, 2025). "Furthermore, we engineered CAR-T cells to express human IL-7, resulting in enhanced anti-tumor efficacy in xenograft models." (PMID 41450878, 2025). "Additionally, IL-7-CAR-T cells significantly prolonged the survival of the tumor-bearing mice compared to CAR-T cells." (PMID 41450878, 2025). "Additionally, IL-7 and IL-21 promote T cell persistence and memory formation, whereas the co-expression of IL-21 and IL-15 has proven effective at controlling tumor growth in hepatocellular carcinoma models." (PMID 40771804, 2025). "A similar process may be occurring in ETP-ALL, where specific niches within the tumor microenvironment provide signals that support proliferation and survival of LSCs including IL-7 and FLT3L." (PMID 39849166, 2025). "Additionally, we engineered CAR-T cells with IL-7, resulting in enhanced proliferation capacity and potent anti-tumor activity." (PMID 41450878, 2025). "Intriguingly, recent studies have reported that in certain tumor types (e.g., hematologic malignancies), exogenous recombinant IL-7 (such as long-acting IL-7) combined with chimeric antigen receptor T (CAR-T) cell therapy suppresses tumor progression by enhancing T cell function." (PMID 41360767, 2025). "It has been demonstrated that IL7R mutations activate downstream IL7R signaling independent of IL7 and promote cell transformation and tumor formation, indicating that IL7R exon 6 mutations are gain-of-function mutations." (PMID 41048344, 2025). "Notably, this receptor overexpression resulted in greater expansion of C.M7R T cells compared to C.M cells when stimulated with irradiated CAPAN1 tumor cells in the presence of recombinant IL-7, consistent with enhanced IL-7 utilization." (PMID 40808942, 2025). "Building on our previous research, which demonstrated the efficacy of preconditioning CAR-T cells with IL-7/IL-15 to augment their anti-tumor capabilities, recent studies have shown promise in combining anti-PD-1 antibodies with CAR-T cell therapy for cancer treatment." (PMID 41450878, 2025). "While we did observe increased frequencies of Granzyme B+ (GzmB+) T cells in the IL-2–expanded group compared with those expanded with IL-7, we also noted an increased baseline frequency of GzmB+ T cells in the unstimulated/IL-2–expanded and tumor-only control groups." (PMID 40244705, 2025). "In conclusion, our study illustrates that providing tumor-localized IL-7 cytokine support via T cells engineered to secrete as well as utilize the cytokine in a dual-antigen targeting binary system enhances the expansion and anti-tumor function of CAR T cells." (PMID 40808942, 2025). "This study aimed to develop a novel recombinant oncolytic vaccinia virus (VVL-GL7) co-expressing granulocyte-macrophage colony-stimulating factor (GM-CSF) and interleukin-7 (IL-7), designed to enhance anti-tumor immunity and synergize with immune checkpoint inhibitors." (PMID 40299475, 2025).